SEMA6A (semaphorin 6A)
Description:
Cell surface receptor for PLXNA2 that plays an important role in cell-cell signaling. Required for normal granule cell migration in the developing cerebellum. Promotes reorganization of the actin cytoskeleton and plays an important role in axon guidance in the developing central nervous system. Can act as repulsive axon guidance cue. Has repulsive action towards migrating granular neurons. May play a role in channeling sympathetic axons into the sympathetic chains and controlling the temporal sequence of sympathetic target innervation. (Microbial infection) Acts as a receptor for P.sordellii toxin TcsL in the in the vascular endothelium.
Synonyms: KIAA1368; SEMAQ; SEMA6A1; SEMA; HT018; VIA
Tractability: Antibody: UniProt places it where antibodies can reach, with high confidence; UniProt predicts a signal peptide or a membrane-spanning region; its Gene Ontology location is reachable by antibodies, with medium confidence. PROTAC: ubiquitination databases record sites on it; its protein half-life has been measured.
Gene: Protein-coding gene on chromosome 5 (116,443,555 to 116,576,161, reverse strand). Ensembl gene ENSG00000092421.
Subcellular location: Cell membrane
Subcellular location (Human Protein Atlas): Nucleoplasm; Intermediate filaments; Nuclear bodies
Pathways (Reactome):
Developmental Biology: Other semaphorin interactions
Gene Ontology:
Molecular function: protein binding; chemorepellent activity; semaphorin receptor binding
Biological process: cellular response to vascular endothelial growth factor stimulus; negative regulation of angiogenesis; negative regulation of cell adhesion involved in sprouting angiogenesis; negative regulation of ERK1 and ERK2 cascade; negative regulation of sprouting angiogenesis; negative regulation of vascular endothelial growth factor signaling pathway; animal organ morphogenesis; apoptotic process; axon guidance; cell surface receptor signaling pathway; cytoskeleton organization; nervous system development; neural crest cell migration; positive regulation of neuron migration; semaphorin-plexin signaling pathway; negative chemotaxis
Cellular component: plasma membrane; axon; membrane
Genetic constraint (gnomAD): Loss-of-function variants: 18 observed, 79.23 expected, observed/expected ratio (o/e) 0.23, 90% interval 0.16 to 0.34. The upper end of that interval is the gene's LOEUF score, 0.34, which puts it in group 1 of 6, group 1 being the genes least tolerant of losing a copy. Missense variants: 1,266 observed, 1,247.1 expected, observed/expected ratio (o/e) 1.02, 90% interval 0.97 to 1.06. Synonymous variants: 573 observed, 500.11 expected, observed/expected ratio (o/e) 1.15, 90% interval 1.07 to 1.23.
Homologues: Orthologues: chimpanzee SEMA6A (99% identical), macaque SEMA6A (99% identical), pig SEMA6A (97% identical), guinea pig SEMA6A (96% identical), dog SEMA6A (96% identical), mouse Sema6a (95% identical), rat Sema6a (94% identical), rabbit SEMA6A (89% identical), tropical clawed frog sema6a (83% identical), zebrafish sema6a (37% identical). Paralogues in human: SEMA6D (46% identical), SEMA6B (40% identical), SEMA6C (34% identical), SEMA3A (21% identical), SEMA3D (21% identical), SEMA4D (21% identical), SEMA4B (21% identical), SEMA5A (20% identical), SEMA3B (20% identical), SEMA5B (20% identical), SEMA4G (20% identical), SEMA3F (19% identical), and 7 more.
Diseases named in the same sentence as SEMA6A in open-access papers:
SEMA6A is named in the same sentence as 45 diseases in open-access papers, as found by Europe PMC text mining. Sharing a sentence is not in itself a finding about the gene and the disease. The quoted sentences say what the papers report.
melanoma (14 papers, 2015 to 2025). A malignant, usually aggressive tumor composed of atypical, neoplastic melanocytes. "In their study, Loria and colleagues observed that SEMA6A is partially engaged in the control of actin cytoskeleton remodeling of BRAF-mutated melanoma, which drives their fast rate of proliferation and survival." (PMID 38067240, 2023). "Overall, our study indicates that SEMA6A is a crucial player in the biology of BRAF-mut melanoma, with high protein expression being associated with worse prognosis in term of OS and PFS of advanced disease and shorter relapse-free interval of early disease." (PMID 35440004, 2022). "First, we show that SEMA6A protein expression is associated with BRAF mutational status in melanoma patients." (PMID 35440004, 2022). "On the contrary, Sema6A positively correlates with melanoma migration and Sema7A is associated with melanoma metastasis." (PMID 30454024, 2018). "Moreover, the inhibition of BRAF and MEK kinases by combined dabrafenib + trametinib treatment of BRAF-mutated melanoma led to the activation of the SEMA6A/RhoA/YAP pathway, which resulted in the remodeling of the cytoskeleton and a reduction in targeted therapy efficiency." (PMID 38067240, 2023). "Cancer research brought out that the level of SEMA6A-protein expression has a prognostic significance in BRAF-mut melanoma patients by regulating the remodeling of actin cytoskeleton via inducing a SEMA6A-RhoA-YAP-pathway." (PMID 40353861, 2025). "SEMA6A regulates the remodeling of the actin cytoskeleton, thereby maintaining the invasive behavior of melanoma cells." (PMID 41259456, 2025). "Our study compared the expression of SEMA6A in melanomas using data from the TCGA and GTEx databases." (PMID 37434634, 2023). "We first verified the association of SEMA6A protein expression with BRAF mutation in the RECI1 cohort, which includes 112 metastatic advanced melanoma patients surgically treated at the Regina Elena National Cancer Institute." (PMID 35440004, 2022). "In BRAFV600E melanoma, SEMA6A was preferentially expressed by western blot and then silencing of SEMA6A induced cell death." (PMID 36034849, 2022). "The expression of SEMA6A protein was higher in melanoma tissues from BRAF-mut patients than in melanoma tissues from BRAF-wt patients." (PMID 36601121, 2022). "Following induction, the expression of SEMA6A was efficiently downregulated in A3 and H2 compared with shCtrl cells, resulting in 20-30% reduction in the number of viable melanoma cells." (PMID 35440004, 2022). "The purpose of the present study is to dissect the role of SEMA6A in the biology of BRAF-mut melanoma, and to explore its predictive potential towards dual BRAF/MEK inhibition." (PMID 35440004, 2022). "In the present study, we provide evidence of the involvement of SEMA6A in the biology of BRAF-mut melanoma and the premise for its possible use as a predictive biomarker." (PMID 35440004, 2022). "Mechanistically, we show that in BRAF-mut melanoma cells, SEMA6A remodels actin cytoskeleton by activating the RhoA-YAP axis." (PMID 35440004, 2022). "Overall these data support the involvement of SEMA6A in the biology of BRAF-mut melanoma and indicate that SEMA6A is a prognostic indicator in this subset of patients." (PMID 35440004, 2022). "We then unravel the molecular mechanism by which SEMA6A regulates the remodeling of actin cytoskeleton thereby sustaining the aggressive behavior of BRAF-mut melanoma cells, and show the involvement of downstream RhoA-YAP cascade." (PMID 35440004, 2022). "Second and to our opinion most relevant, we show that SEMA6A is involved in the mechanisms that regulate the sensitivity of BRAF-mut melanoma cells to dual BRAF/MEK inhibition therapy and acts as a crucial mediator of melanoma-stroma communication." (PMID 35440004, 2022). "Of note, the evidence that Sema4D, together with Sema6A, is the most expressed protein in melanoma, being expressed in 100% of melanoma tissues." (PMID 33858502, 2021).
melanoma (continued). "Expression of FAM174B, MAD1L1, SCARB1, MFSD12, SEMA6A, SLC45A2, and TBC1D16 was found to be upregulated and associated with worse OS in melanoma patients, while only MFSD12 and SLC45A2 were associated with worse DFS for melanoma patients." (PMID 30385854, 2019). "In particular, amplification of SEMA5A and SEMA6A loci (found in 20% and 30% of the melanoma, respectively) were consistent with their increased mRNA expression in melanomas compared to nevi." (PMID 27095580, 2016). "In conclusion our results revealed that BRAFV600E melanomas express high level of Sema6A and MICAL1 whose functions are strongly involved in the mechanisms that control cell proliferation and survival." (PMID 25576923, 2015). "Annexin-V/PI staining assays indicated that Sema6A depletion induced apoptosis, associated with caspase 3/7 activation, in BRAFV600E clones 2/56 and 2/59 and in melanoma cell line 10538, with effects already evident at 24-36h." (PMID 25576923, 2015). "Moreover, SEMA6A overexpression prompted proliferation and markedly enhanced invasiveness in melanoma cells." (PMID 41259456, 2025). "SEMA6A activated pro-survival and pro-proliferative cell signaling in melanoma cells." (PMID 41259456, 2025). "Additionally, SEMA6A plays a pivotal role in orchestrating the coordinated escape of melanoma cells from concurrent BRAF/MEK inhibition, signifying its potential as a dependable marker for immediate therapeutic benefits of such inhibition." (PMID 38036577, 2023). "By an unbiased screening of different single cell clones derived from the same melanoma patient and mutually carrying BRAFV600E or NRASQ61R mutations, we previously identified semaphorin SEMA6A as a protein whose expression is associated with BRAFV600E mutation." (PMID 35440004, 2022). "SEMA6A has been shown to be deregulated together with many other cancer-related genes in the complex mechanism driven by BRAFV600E on melanoma tumorigenesis; Guo and collegues also indicated the transcription factor MITF as a main mediator of BRAFV600E-driven transcription reprogramming." (PMID 35440004, 2022). "Furthermore, the activity of SEMA6A/RhoA/YAP axis is induced by dual BRAF/MEK inhibition by dabrafenib+trametinib and, in an environmental-mimicking condition of melanoma cells and fibroblasts co-culture, is associated with reduced targeted therapy efficacy." (PMID 35440004, 2022). "Indeed, the expression of SEMA6A is associated with insensitivity to both treatments only in co-culturing condition, highlighting the role of SEMA6A as a critical transducer of signals from melanoma-stroma interactions." (PMID 35440004, 2022). "In addition, SEMA6A regulates actin cytoskeleton remodeling through RhoA-dependent activation of YAP in BRAF-mut melanoma cells." (PMID 36601121, 2022). "Overall, our results indicate that SEMA6A contributes to microenvironment-coordinated evasion of melanoma cells from dual BRAF/MEK inhibition and it might be a good candidate predictor of short-term benefit from dual BRAF/MEK inhibition." (PMID 35440004, 2022). "Similarly, increased overexpression of Sema6A, in NRAS mutated cells, induced anchorage-independent growth and enhanced invasion, thus, indicating Sema6A as a potential therapeutic target for melanoma treatment." (PMID 33858502, 2021). "Taken together these results suggested that Sema6A promotes survival of BRAF-mutant melanoma cells." (PMID 25576923, 2015). "Interestingly, PI3K and MAPK activity appeared to be regulated downstream of Sema6A, as their phosphorylation levels clearly correlated with Sema6A depletion, suggesting that this semaphorin can regulate major pathways supporting melanoma cell viability." (PMID 25576923, 2015). "In nevi, Sema6A and Mical-1 expression was comparable to the levels found in WT melanoma." (PMID 25576923, 2015).
melanoma (continued). "In attempts to find molecules regulating aggressiveness of BRAFV600E melanoma cells, by whole-genome array we found that SEMA6A and MICAL1, two genes of the SEMA/PLEXIN signaling pathway, were over-expressed in BRAFV600E clones compared to NRASQ61R clones isolated from the same metastasis." (PMID 25576923, 2015). "In vertebrates, this molecule interact with class A Plexins, suggesting that it could be a mediator of Sema6A signaling in melanoma cells." (PMID 25576923, 2015). "Furthermore, depletion of Sema6A in NRASQ61R melanoma clones down-regulated their capability to invade (P≤0.001)." (PMID 25576923, 2015). "Overall these data support the involvement of SEMA6A in fibroblasts-induced protection of melanoma cells from the anti-tumor activity of dual BRAF/MEK inhibition and indicate that SEMA6A might be a good candidate predictor of short-term benefit from dual BRAF/MEK blockade." (PMID 35440004, 2022). "Interestingly, SEMA6A is overexpressed in BRAFV600E melanoma cells." (PMID 30374140, 2018). "Recent studies have illuminated SEMA6A's role in governing the viability and proliferation of BRAFV600E human melanoma cells." (PMID 38036577, 2023). "Sema6A depletion strongly induced PARP cleavage in clone 2/21 and reduced total PARP in the clones 2/56 and 2/59 and in the melanoma cell line 10538." (PMID 25576923, 2015). "We also found high expression of both Sema6A and Mical1 in BRAFV600E cells derived from seven different melanoma cell lines isolated from primary tumor or from lymph node metastases." (PMID 25576923, 2015). "The results demonstrated that Sema6A and Mical-1 were significantly more expressed in BRAFV600E than in WT melanomas (P<0.02 and P<0.009, respectively)." (PMID 25576923, 2015). "Taken together, these results support the notion that both Sema6A and Mical1 promote cell survival, and inhibit cell death of BRAFV600E melanomas through different pathways." (PMID 25576923, 2015). "Real-time PCR, Western blot and immunohistochemistry confirmed preferential expression of Sema6A and Mical1 in BRAFV600E melanoma." (PMID 25576923, 2015). "Taken together these results suggest that Sema6A and Plexin-A4 have distinct roles in regulating biological functions in BRAF-mutant melanoma cells." (PMID 25576923, 2015). "In addition, we observed that SEMA6A regulates actin cytoskeleton remodeling, thereby sustaining proliferation and survival of BRAF-mut melanoma cells." (PMID 35440004, 2022). "In BRAF-mut melanoma cells, SEMA6A coordinates actin cytoskeleton remodeling by the RhoA-dependent activation of YAP and dual BRAF/MEK inhibition by dabrafenib+trametinib induces SEMA6A/RhoA/YAP axis." (PMID 35440004, 2022). "However, our results indicate that surrounding fibroblasts play an essential role in coordinating evasion of co-cultured BRAF-mut melanoma cells from both BRAF and combined BRAF/MEK inhibition in a SEMA6A-dependent manner." (PMID 35440004, 2022). "BRAF mutant melanoma cells, when compared to NRAS mutant ones, showed higher expression of Sema6A." (PMID 33858502, 2021). "Surprisingly, Mical1 silencing did not change the actin cytoskeleton organization, indicating that its role in BRAFV600E melanoma cells is not overlapping with that of Sema6A." (PMID 25576923, 2015). "Overall, our data suggest that Sema6A and Mical1 may represent new potential therapeutic targets in BRAFV600E melanoma." (PMID 25576923, 2015). "We tested whether Sema6A and Mical1 could exert a significant pro-tumoral role in BRAFV600E melanomas by contributing to regulate their growth, survival, and invasion." (PMID 25576923, 2015). "However there is no previous evidence of the role of SEMA6A in melanoma-microenvironment interactions." (PMID 35440004, 2022). "Moreover, a recent RNA-sequencing analysis conducted on SkMel-28 melanoma cells reveals a significant downregulation of SEMA6A following MITF knock out, suggesting the possible involvement of MITF in BRAFV600E-driven regulation of SEMA6A." (PMID 35440004, 2022).
lung carcinoma (10 papers, 2018 to 2025). "Lower expression of SEMA6A has been linked to lung cancer and higher expression with higher overall survival in Glioblastoma." (PMID 38950330, 2024). "Semaphorin-6A (SEMA6A), a protein initially known as a regulator of axonal guidance, is down-regulated in lung cancer tissue, and low levels of SEMA6A are associated with cancer recurrence." (PMID 31527696, 2019). "SEMA6A expression was downregulated in lung cancer tissues, and its overexpression inhibited lung cancer cell proliferation both in vitro and in vivo." (PMID 41259456, 2025). "SEMA6A inhibited the migration ability of lung cancer cells through the NRF2/HMOX1 axis, and SEMA6A overexpression significantly reduced the migration of lung cancer cells." (PMID 41259456, 2025). "Under-expression of Sema6a has been reported in some other cancers, such as lung cancer and oral carcinoma." (PMID 39596610, 2024). "Increased expression of SEMA6A has been reported to be associated with tumor apoptosis in human oral cancer cells, whereas low expression of SEMA6A in lung cancer is correlated with high recurrence in the clinical setting." (PMID 37434634, 2023). "A recent work demonstrated that low Sema6A expression correlates with high tumor recurrence rates in lung cancer patients." (PMID 33537086, 2021). "In conclusion, the present study identified a novel suppressor of lung cancer cell migration, SEMA6A, which attenuates migration by inducing the NRF2/HMOX1 axis." (PMID 31527696, 2019). "Similar to these tumor suppressor semaphorins, semaphorin 6A (SEMA6A) significantly inhibited the growth of lung cancer cells when losing either SEMA domain or whole extracellular region." (PMID 31527696, 2019). "After SEMA6A was demonstrated to modulate lung cancer cell migration, we wanted to identify the genes downstream of SEMA6A in the migration inhibition pathway." (PMID 31527696, 2019). "The SEMA6A-derived regulation pathway in migration was also found to occur in other lung cancer cell lines, such as A549 and CL1-5." (PMID 31527696, 2019). "Our data highlight a novel feature of SEMA6A, which is that SEMA6A can reduce lung cancer cell migration through the NRF2/HMOX1 axis in a manner dependent on its cytosolic region." (PMID 31527696, 2019). "In this study, we found that the migration capability of H1299 lung cancer cells decreased with SEMA6A overexpression, while it increased with SEMA6A silencing." (PMID 31527696, 2019). "This study suggests a novel function of SEMA6A in inducing apoptosis via FADD binding in lung cancer cells." (PMID 30518871, 2018). "Based on such evidence, it can be asserted that the extracellular domain of SEMA6A not only modulates responses for plexin-related signaling, but also functions as a key regulator in SEMA6A cytosolic domain-induced apoptosis in lung cancer cells." (PMID 30518871, 2018). "Given the low expression of SEMA6A in lung cancer cells, we studied the effects of SEMA6A overexpression on cell proliferation, colony formation, and apoptosis in A549 and H1299 cells." (PMID 30518871, 2018). "Our results showed that overexpression of SEMA6A reduced the growth of lung cancer cells in vitro and in vivo, and silencing SEMA6A increased the proliferation of normal lung fibroblasts." (PMID 30518871, 2018). "In the present study, full length SEMA6A and various truncations were transfected into lung cancer cells to investigate the role of the different domains of SEMA6A in cell proliferation and survival, apoptosis, and in vivo tumor growth." (PMID 30518871, 2018). "In human lung cancer lines, overexpression of SEMA6A resulted in decreased migration due to the activation of the nuclear factor erythroid 2 p45-related factor 2 (NRF2)/heme oxygenase-1 (HMOX) axis, which translated into increased overall survival (OS) and a decreased recurrence rate." (PMID 38067240, 2023). "Upregulation of SEMA6A levels in mice with lung cancer resulted in lower tumor volume." (PMID 38067240, 2023).